NR2E3 (nuclear receptor subfamily 2 group E member 3)
Diseases named in the same sentence as NR2E3 in open-access papers (continued):
Sharing a sentence is not in itself a finding about the gene and the disease.
liver cancer (5 papers, 2017 to 2025). An epithelial or non-epithelial malignant neoplasm that arises from the liver. "Lastly, we demonstrated that both AHR and NR2E3 are significantly associated with good clinical outcomes in liver cancer." (PMID 28878246, 2017). "Our data suggested that NR2E3 loss caused, which would probably promote susceptibility to and progression of liver cancer, in part, via modulating LSD1 redistribution and activity." (PMID 28878246, 2017). "The tumor suppressive role of NR2E3 during liver cancer development is currently under investigation." (PMID 28878246, 2017). "We further demonstrated that higher expression of NR2E3 or AHR in liver cancer patients is strongly correlated with good clinical outcomes." (PMID 28878246, 2017). "Correspondingly, liver cancer patients who expressed high levels NR2E3 are significantly correlated with good prognosis." (PMID 28878246, 2017). "Collectively, these results showed for the first time that both AHR and NR2E3 are good prognostic indicators and may function as tumor suppressor genes during the development of liver cancer." (PMID 28878246, 2017). "Together, our results reveal a novel link between NR2E3, AHR, and liver cancer via LSD1-mediated H3K4me2 histone modification in liver cancer development." (PMID 28878246, 2017). "Here, we found that an orphan nuclear NR2E3 maintains AHR expression, and forms an active transcriptional complex with transcription factor Sp1 and coactivator GRIP1 in MCF-7 human breast and HepG2 liver cancer cell lines." (PMID 28878246, 2017).
retinoblastoma (5 papers, 2022 to 2025). A malignant tumor that originates in the nuclear layer of the retina. "Overall, our findings offer promising combinatorial treatments targeting NR2E3 in cervical cancer and retinoblastoma cells, highlighting NR2E3 as a novel molecular vulnerability in solid tumors." (PMID 39809731, 2025). "Orphan Nuclear Receptor subfamily 2 group E member 3 (NR2E3) was initially cloned from human retinoblastoma Y79 cells and a mouse λZAP eye cDNA library in 1999." (PMID 39809731, 2025). "The drug repurposing screen in retinoblastoma Y79 cells, from which NR2E3 was first cloned, revealed that two proteasome inhibitors, Bortezomib and Carfilzomib, synergized with 11a to induce cell death at higher concentrations." (PMID 39809731, 2025). "Our Western blot analysis of NR2E3 in retinoblastoma cells showed that biliverdin induced the level of NR2E3 protein by approximately twofold (2.0 ± 0.2 fold elevation by 1 μM biliverdin, n = 3) in a dose-dependent manner (not repeated)." (PMID 35508617, 2022). "Therefore, we conducted drug repurposing screens in an FDA-approved anti-cancer drug library (NCI AOD X version) in human cervical cancer HeLa cells and human retinoblastoma Y79 cells, both of which exhibit NR2E3 expression." (PMID 39809731, 2025). "However, the early L/M cone precursors’ expression of NR2E3 and NRL RNAs suggests that their presence in retinoblastomas reflects their normal expression in the L/M cone precursor cells of origin." (PMID 40767624, 2025).
Leber congenital amaurosis (4 papers, 2019 to 2025). Leber congenital amaurosis (LCA) is a retinal dystrophy defined by blindness and responses to electrophysiological stimulation (Ganzfeld electroretinogram (ERG)) below threshold, associated with severe visual impairment within the first year of life. "Mutations in Crx can cause Leber congenital amaurosis (LCA), cone-rod dystrophy (CRD), and Retinitis pigmentosa (RP), while Nrl and Nr2e3 mutations can cause RP and enhanced S-cone syndrome." (PMID 31795518, 2019).
Atrophy (3 papers, 2016 to 2023). Any weakening or degeneration, especially through lack of use. "Maculopathy progression in NR2E3-associated retinopathy, including the dynamic progression of presentation, resorption, and atrophy, was observed based on multimodal retinal images in our cohort." (PMID 37628579, 2023).
Nystagmus (3 papers, 2018 to 2025). Rhythmic, involuntary oscillations of one or both eyes related to abnormality in fixation, conjugate gaze, or vestibular mechanisms. "Subcapsular cataract and nystagmus as in one and two of our patients respectively is not frequently reported in ESCS patients carrying NR2E3 mutations." (PMID 29385733, 2018). "No patients with nystagmus were reported, whereas one of our patients was affected, suggesting a younger age of onset or a more severe presentation in some cases of NRL-associated ESCS as compared with NR2E3-related ESCS." (PMID 36140584, 2022).
retinoschisis (3 papers, 2018 to 2024). An inherited or acquired disorder characterized by splitting of the retina into two layers. "In a few cases, NR2E3 mutations were also described in patients with retinoschisis." (PMID 38790275, 2024).
blinding (2 papers, 2017 to 2020). "Second, mutations in the NRL gene (along with its downstream effector NR2E3) are causal of blinding disorders that remain unchecked." (PMID 33299975, 2020).
deafness (2 papers, 2017). An inherited or acquired condition characterized by the complete loss of the ability to hear from one or both ears. "Usher gene mutations were found in most patients with atypical Usher syndrome, but the diagnosis was adjusted in case of double homozygosity for mutations in OTOA and NR2E3, genes implicated in isolated deafness and RP." (PMID 28944237, 2017).
hepatocellular carcinoma (2 papers, 2017 to 2024). A malignant tumor that arises from hepatocytes. "Consistently, the results obtained from a publically available database of cancer expression profiles (ww.oncomine.org) showed decreased NR2E3 mRNA expression in human cirrhotic and hepatocellular carcinoma relative to normal liver tissues." (PMID 28878246, 2017). "Nonetheless, a precise tumor suppressive and epigenetic role of NR2E3 in hepatocellular carcinoma (HCC) development remains unclear." (PMID 38790135, 2024).
hyperopia (2 papers, 2018 to 2022). A refractive error in which rays of light entering the eye parallel to the optic axis are brought to a focus behind the retina, as a result of the eyeball being too short from front to back. "Additionally, another frequently reported homologous clinical sign is the presence of elevated hyperopia in NR2E3-associated ESCS and NRL-associated ESCS." (PMID 36140584, 2022).
Macular schisis (2 papers, 2023). Splitting of the retina in the macular region. "The presence of macular schisis and a double ring on autofluoresence, biallelic NR2E3 mutations should be considered." (PMID 36067420, 2023). "In our cohort, macular schisis-like changes, retinal pigment epithelial degeneration, and a hyper-autofluorescent ring around the vascular arcades may represent the progression of both dominant and recessive NR2E3-associated retinopathy." (PMID 37628579, 2023). "However, similar clinical manifestations, such as macular schisis and hyper-autofluorescent rings around the vascular arcades, have been reported to present in both ADRP and ARRP associated with NR2E3, despite the differing pathogeneses." (PMID 37628579, 2023).
pigmentary retinal degeneration (2 papers, 2012 to 2023). "Mutations in NR2E3 have been associated with a range of overlapping phenotypes, including ESCS, clumped pigmentary retinal degeneration, Goldman-Favre syndrome, and dominant as well as recessive RP." (PMID 22605927, 2012).
cervical cancer (1 paper, 2025). A primary or metastatic malignant neoplasm involving the cervix. "In summary, we have revealed how 11a and Romidepsin synergize to suppress cervical cancer, providing mechanistic insights into targeting NR2E3 in cancer." (PMID 39809731, 2025).
Cirrhosis (1 paper, 2017). A chronic disorder of the liver in which liver tissue becomes scarred and is partially replaced by regenerative nodules and fibrotic tissue resulting in loss of liver function. "We next investigated whether NR2E3 levels are altered in precancerous liver diseases such as cirrhosis and liver tumor by comparing the protein levels between diseased and normal liver tissues." (PMID 28878246, 2017).
depression (1 paper, 2024). "In this study, we found that knockdown of Nr2e3 in the hippocampus caused significantly depression‐like behaviors, suggesting that Nr2e3 had an antidepressant effect in the central never system." (PMID 38881534, 2024). "Because deficiency of Tet2 causes depressive behaviors in mice, we further determined whether knockdown Nr2e3 in the hippocampus also causes depression‐like behaviors in mice." (PMID 38881534, 2024). "In this study, we identified Nr2e3 as a novel transcriptional regulator of Tet2 expression in depression." (PMID 38881534, 2024). "The present study identified Nr2e3 as an essential transcription factor of Tet2, elucidated the upstream regulatory mechanism of Tet2, and clarified a new mechanism of depression by which Nr2e3 is involved in the regulation of synaptic plasticity through regulating Tet2." (PMID 38881534, 2024). "Since Nr2e3 may play an antidepressant role in depression, we aimed to identify Nr2e3 as a therapeutic target of antidepressant drug development." (PMID 38881534, 2024). "Based on these findings, we hypothesized that Nr2e3 may be the primary regulator of Tet2 in the context of depression." (PMID 38881534, 2024). "Our study demonstrated that Nr2e3 is a promising target for the development of novel antidepressant therapy and may be an early biological marker for depression." (PMID 38881534, 2024). "Therefore, we investigated the expression of Nr2e3 in other depression‐related brain regions except the hippocampus." (PMID 38881534, 2024).
diabetes (1 paper, 2024). "To confirm this, we then analyzed several known clock-controlled genes for the retina (Adcy1, Drd4, Nr2e3, Cys1, Plekbh1, Usp2) that also showed amplitude changes but no phase changes, indicating that the retinal clock was entrained to the 12L:12D cycle at this stage of diabetes." (PMID 38039846, 2024).
multiple myeloma (1 paper, 2025). "In line with this, we recently constructed all of the five NR2E3 nonsynonymous mutations detected in multiple myeloma patients, one of which came to be a loss-of-function mutation." (PMID 39809731, 2025). "Given that NR2E3 has been shown to repress the MYC pathway, it is plausible that NR2E3E387K may synergize with NRASQ61R to promote the development of multiple myeloma." (PMID 39809731, 2025).
Retinal dysplasia (1 paper, 2025). Abnormal growth and differentiation, structure and appearance of the retina present from birth.
Usher syndrome (1 paper, 2017). A syndromic diseae characterized by the association of sensorineural deafness (usually congenital) with retinitis pigmentosa and progressive vision loss. "In patient 93, the specific retinopathy due to NR2E3 mutation homozygosity could have indicated a diagnosis distinct from Usher syndrome, but congenital deafness resulting from the homozygous deletion of OTOA is indistinguishable from the hearing impairment in USH1." (PMID 28944237, 2017).
uterine cancer (1 paper, 2025). Primary or metastatic malignant neoplasm involving the uterine corpus and/or the cervix.
retinopathies (14 papers, 2009 to 2024). "Genotype–phenotype correlation analysis was performed based on autosomal dominant and recessive retinopathy associated with NR2E3." (PMID 37628579, 2023). "NR2E3 retinopathies are very rare, we describe three patients in whom NR2E3 mutations have been identified, of which two are novel." (PMID 33138239, 2020). "Recessively-inherited NR2E3 gene mutations cause an unusual retinopathy with abnormally-increased short-wavelength sensitive cone (S-cone) function, in addition to reduced rod and long/middle-wavelength sensitive cone (L/M-cone) function." (PMID 31117170, 2019). "Retrospectively, these patients had additional abnormalities (in case of PEX26‐associated PBD) or a distinct, NR2E3‐typical form of retinopathy." (PMID 28944237, 2017). "NRL, CRX, and NR2E3 are key transcription factors that regulate photoreceptor differentiation, and mutations in these lead to retinopathies." (PMID 19898638, 2009). "In terms of treatment strategies to NR2E3-associated retinopathies, fate-switch to developmentally altered photoreceptors might be unrealistic." (PMID 37181651, 2023). "Common phenotypes were present in both types of NR2E3-associated retinopathy." (PMID 37628579, 2023). "Our data might further enrich our understanding of NR2E3 variants and associated inherited retinopathy." (PMID 37628579, 2023). "The three patients share some of the typical distinctive features of NR2E3 retinopathies, as well as a novel clinical observation of foveal ellipsoid thickening." (PMID 33138239, 2020). "In view of the variable phenotypes, we propose that the three entities ESCS, CPRD and GFS are renamed NR2E3 retinopathies, listing key features, which would include visual acuity, field measurements, the presence of oedema, and electrophysiological characterisation to help in determining prognosis." (PMID 33138239, 2020). "To date, no clear phenotype-genotype correlation has been identified in NR2E3 retinopathies." (PMID 33138239, 2020). "Moreover, none of the three patients reported here had cystoid or schitic changes at the macula, as has been described as a typical or common appearance in NR2E3 recessive retinopathies." (PMID 33138239, 2020). "Of interest, neither of the two NR2E3 gene variants found in this case report have been linked to any form of retinopathy." (PMID 30285900, 2018). "This pattern has also been seen in other IRDs including dominant NR2E3- and EYS-related retinopathies, representing in both cases the boundaries between affected and unaffected retina." (PMID 37331655, 2023). "The current signed-off version of Genomics England’s PanelApp Retinal Disorders virtual panel gene list (version v2.195) includes all six main CACD genes, plus CRX, NR2E3, NRL, RAX2 and also VSX2, but as low-evidence gene (red list)." (PMID 35656327, 2022).
cancer (8 papers, 2017 to 2025). A tumor composed of atypical neoplastic, often pleomorphic cells that invade other tissues. "This highlights the potential interplay between NR2E3 mutations and other genetic alterations in cancer pathogenesis." (PMID 39809731, 2025). "In our analysis of cancer cases from The Cancer Genome Atlas (TCGA), we observed NR2E3 mutations altering the protein sequence." (PMID 39809731, 2025). "Our observations suggest a potential role for NR2E3 in cancer predisposition, as all reported NR2E3 SNVs have been identified as germline mutations." (PMID 39809731, 2025). "Currently, Nr2e3-Knock out and -Knock in mouse strains are available for in vivo evaluating NR2E3’s roles in cancer predisposition by cross-breeding with co-occurring gene mutations." (PMID 39809731, 2025). "At cellular level, the loss of NR2E3 increases the acquisition of aggressive cancer cell phenotype and tumorigenicity and upregulates key genes in the WNT/β‐catenin pathway with increased chromatin accessibility." (PMID 38790135, 2024). "Consistently, NR2E3 depletion was found to enrich the Wnt/β‐catenin signaling pathway, along with other critical signaling pathways implicated in cancer, including epithelial‐mesenchymal transition." (PMID 38790135, 2024). "Significant associations between NR2E3 mutations and these cancer types were evident compared to the reference population in the “All of Us” database which encompasses diverse demographic groups (p < 0.05, high OR with 95% CI, adjusting for race, sex, and age)." (PMID 39809731, 2025). "Furthermore, these cancer-associated NR2E3 mutations often co-occur with mutations in various tumor-suppressing or tumor-promoting genes." (PMID 39809731, 2025). "The increasing availability of databases highlighting the connections between NR2E3 SNVs and various solid tumors underscores the importance of further exploring the roles of these SNVs in cancer." (PMID 39809731, 2025). "Our efforts to study the functions of NR2E3 will shed light on the application of NR2E3 in gene therapy for cancer as well as for enhanced S-cone syndrome, one type of inherited vision loss." (PMID 39809731, 2025). "Collectively, our result showed that 11a is able to penetrate the solid tumor to agonize NR2E3, which is of a great value as an anti-cancer drug candidate." (PMID 39809731, 2025). "To further elucidate NR2E3’s roles in cancer, we expressed HA-tagged NR2E3 protein derivatives, including the full-length isoform (FL), DNA-binding domain (DBD), ligand-binding domain (LBD), and short isoform (short), in HeLa cells." (PMID 39809731, 2025).